ABCC4 (ATP binding cassette subfamily C member 4 (PEL blood group))
Diseases named in the same sentence as ABCC4 in open-access papers (continued):
Sharing a sentence is not in itself a finding about the gene and the disease.
tumor (continued). "Taken together, our findings show that MRP4/ABCC4 has a relevant role in tumor growth and apoptosis and in the eradication of LSCs, providing the basis for a novel promising target in AML therapy." (PMID 25301721, 2014). "Here, we studied the role of MRP4/ABCC4 in tumor progression in a mouse xenograft model and in leukemic stem cells (LSCs) differentiation." (PMID 25301721, 2014). "Here, we show that MRP4/ABCC4 blockade strongly reduced tumor growth inducing cell cycle arrest and apoptosis in vivo." (PMID 25301721, 2014). "Down-regulation of ABCC4 expression significantly enhanced irradiation-induced suppression of tumor growth in xenograft model." (PMID 24454870, 2014). "MRP4/ABCC4 is able to transport several eicosanoids, including prostaglandin E2, that have implications for tumor development, growth, and angiogenesis and the response of tumors to cytotoxic chemotherapy." (PMID 22837662, 2012). "Several upregulated ABC transporters, such as ABCA12, ABCC1 and ABCC4, were also identified, which may contribute to immune-modulatory molecule efflux and further alter the tumor microenvironment." (PMID 39860532, 2025). "Next, we transplanted RM1 cells (ABCC4-/-) into C57 mice with complete immune system and observed significant growth restriction compared to control group, while observed similar tumor growth rates in Rag-I mice with incomplete immune systems." (PMID 39247809, 2024). "Next, we found the expression of TNF-α, IFN-γ and CD107a representative of cytotoxicity in CD8+ T cells were all elevated in the the ABCC4-KO group, implying that genetic ablation of ABCC4 in tumor cells could restore the anti-tumor effects of CD8+ T cells." (PMID 39247809, 2024). "Furthermore, in vivo depletion of CD8+ T cells in C57 mice caused similar tumor growth rates in the ABCC4-KO group and control group, suggesting that the supressive effects of ABCC4 ablation in tumor cells relied on restoration of CD8+ T cells." (PMID 39247809, 2024). "We found that ABCC4 was significantly upregulated, whereas ABCG2 was downregulated in primary tumours in comparison to normal colon tissue." (PMID 38067326, 2023). "In our differential gene expression analysis and GSEA, most enriched genes are involved in tumor aggressiveness and drug resistance including ABHD2, ABCC4, CLN5 intracellular trafficking protein, and insulin like growth factor 2 receptor." (PMID 35054064, 2022). "It was observed in the TCGA database that ABCC1, ABCC4, ABCC5, and ABCC10 were significantly upregulated in tumor tissues, while ABCC6 and ABCC7 were downregulated in HCC tissues." (PMID 35342392, 2022). "Results showed that the expression of five parent gene (PRIM2, ABCC4, UTRN, ABHD2, and MTHFD2L) was also significant increase in tumor compared to those in normal tissues." (PMID 34852706, 2021). "Recently, many studies have illustrated the relationship between ATP-binding cassette subfamily C member 4 (ABCC4) and tumor chemoresistance." (PMID 34094932, 2021). "Studies of drug-resistant cell lines derived from human neoplasms identified amplifications of at least 13 ABC transporter genes, including ABCB1, ABCC1 and ABCC4." (PMID 32206879, 2020). "Immunohistochemistry gradings for 5 biomarkers (CD44, ABCC4, ABCC11, N-Cadherin and pan-Cadherins) and 3 clinical parameters (tumor size, tumor grade and node status) of 298 patient cohort were used to develop a machine learning based statistical algorithm." (PMID 30894144, 2019). "In line with our previous observations, the tumor markers AMACR, CAMKK2, TMEFF2, REPS2 and ABCC4 were significantly expressed in AMACR high cells as compared to AMACR low cells." (PMID 25514598, 2015).
tumor (continued). "Next, 200 cells from the high and low gate were sorted for qPCR analysis for a subset of tumor markers such as AMACR, CAMKK2, TMEFF2, REPS2 and ABCC4." (PMID 25514598, 2015). "Some tumor markers such as AMACR, TMEFF2 and ABCC4 were also expressed in mesenchymal cells or lymphocytes at levels comparable to AMACR low cells." (PMID 25514598, 2015). "It uses a machine learning algorithm to compute a risk score for distant recurrence over a timeline of five years with the inputs from IHC gradings of five biomarkers (CD44, ABCC4, ABCC11, N-Cadherin, and pan-Cadherin) along with three clinical parameters (node status, tumor size, and tumor grade)." (PMID 39944436, 2025). "The cibersort results of tumor ABCC4 expression and CD8 scores were consistently negative correlated in PRAD." (PMID 39247809, 2024). "Additionally, our findings demonstrate a functional connection between ABCC4/MRP4 levels and collagen content, inflammation, and communication pathways like Wnt signaling that are crucial players in the tumor-stroma interface." (PMID 39114357, 2024). "Moreover, metastasis presented higher ABCC1, ABCC3 and ABCC4 expression and lower SLC22A1 and ABCC10 expression than the primary tumor." (PMID 36982681, 2023). "Interestingly, PDE inhibitors were shown to inhibit several MDR transporters (e.g., ABCC4/MRP4, ABCC5/MRP5, ABCB1/P-gp, ABCG2/BCRP), thus enhancing chemotherapeutic drug accumulation in tumor cells and efficacy." (PMID 35008687, 2021). "Our study reveals a positive correlation between ABCC4 expression and a pro-mesenchymal phenotype, along with a negative correlation with pro-epithelial TF and markers across multiple transcriptomic datasets comprising PDAC tumor samples and preclinical models." (PMID 39114357, 2024). "Furthermore, we showed that ABCC4, DAG1, and SLC39A8 proteins are significantly downregulated in tumors compared to NATs, suggesting that they may play the role of tumor suppressors." (PMID 36499305, 2022). "Human tumor transcriptomic data for 377 HCC patients also show a positive correlation of multiple ABC transporters including the ABCB1, ABCC3, ABCC9 and ABCG2 with GHR expression, while ABCC1,ABCC4 and ABCG1 levels correlated with IGF1R expression, confirming our in vivo observations." (PMID 35865483, 2022). "As expected, HPAF-II xenografts showed glandular structures, typical of highly differentiated tumors, with higher FOXA1 expression, whereas PANC-1 xenografts exhibited solid and compact tumor sheets without lumens, indicative of poor differentiation, along with higher GATA2 and ABCC4 expression." (PMID 39114357, 2024). "The average expression level of the ABCA3 (p = 0.007), ABCB9 (p = 0.000), ABCC1 (p = 0.000), ABCC4 (p = 0.000), ABCC5 (p = 0.000), and ABCC6 (p = 0.000) genes was statistically significantly higher in patients without tumor cell infiltration in the lymph vessels." (PMID 36674773, 2023).
inflammation (3 papers, 2013 to 2021). Aberrant reaction of the microcirculation characterized by movement of fluid and leukocytes from the blood into extravascular tissues. "Although ABCC4 has not previously been associated with uterine inflammation in dogs, it is known that the protein has central functions in the reproductive system, and its role in transporting prostaglandins (PGs) in the endometrium is well-established." (PMID 34404837, 2021).
blood cancer (2 papers, 2012 to 2016). "The cAMP transporter ABCC4 has increased expression in blood cancer cells as compared to normal hematopoietic cells, and its expression decreases significantly upon cell differentiation." (PMID 27129155, 2016).
ABCC4 also shares sentences with these, for which no sentence is quoted: infection (5 papers); cardiovascular disease (3); coronary artery disease (3); endometriosis (3); gallstones (3); liver diseases (3); liver fibrosis (3); renal disease (3); alopecia (2); cervical cancer (2); Cholestatic liver disease (2); chronic kidney disease (2); glaucoma (2); HIV-1 infection (2); hyperuricemia (2); lymphoma (2); metabolic disease (2); mucositis (2); non-alcoholic fatty liver disease (2); renal cell carcinoma (2); renal fibrosis (2); type 2 diabetes (2); viral infection (2); acute pancreatitis (1); acute renal failure (1); adenocarcinoma (1); AIDS (1); alcoholic liver diseases (1); allergic asthma (1); anemia (1).
A further 45 diseases each share a sentence with ABCC4 in 1 paper.